LGALS1 (galectin 1)
Diseases named in the same sentence as LGALS1 in open-access papers (continued):
Sharing a sentence is not in itself a finding about the gene and the disease.
tumor (continued). "Using this approach, galectin-1 was silenced not only in tumor cells but also in the TME." (PMID 35008740, 2021). "Both ITGB1 and LGALS1 mediate cell proliferation, migration and tumour progression." (PMID 34403115, 2021). "Moreover, galectin-1 has a stimulating effect on angiogenesis, since specific galectin-1-neutralizing antibodies were shown to suppress angiogenesis and tumor formation in vivo." (PMID 34209508, 2021). "Thijssen and colleagues have demonstrated a central role for galectin-1 in tumor angiogenesis." (PMID 35008740, 2021). "A continuous increased expression of SATB1 has been described to convert inflammatory anti-tumor DCs into pro-tumor DCs by enhanced secretion of pro-tumorigenic cytokine IL-6 and immunosuppressive factor Galectin-1, activating immune-evasive pathways in these cells." (PMID 33761971, 2021). "The overexpression of LGALS1 promoted subcutaneous tumor growth and lung metastasis in nude mice." (PMID 34260413, 2021). "We did not observe any association between galectin-1 expression and any clinicopathologic parameters including age, primary tumor location, histological grade, AJCC 7th staging, T classification and N classification." (PMID 34201887, 2021). "However, in tumor cells that overexpress galectin-1, release of miR-1983-containing exosomes is strongly diminished, and this process is subsequently repressed." (PMID 35008740, 2021). "Galectin-1 inhibitor combined with sorafenib can further decrease the tumor size." (PMID 34778306, 2021). "Moreover, in a galectin-1 knockout (KO) mouse model, tumor growth was markedly impaired and this effect was attributed to a weak tumor angiogenesis." (PMID 33352759, 2020). "Another study found that tumor derived exosomal protein galectin-1 induced a suppressor phenotype and may be a potential therapeutic target to prevent T cell dysfunction and enhance anti-tumor immune responses." (PMID 32901082, 2020). "Further, shikonin suppressed tumor growth and promoted apoptosis and autophagic cell death in tumor tissues, and also upregulated the level of galectin-1 in tumor tissues and could a promising target for shikonin." (PMID 31892852, 2020). "However, tumor cells can domesticate these cells, and alter their maturation and activation through galectin-1 and IL-6 to confer a pro-tumorigenic phenotype that promotes tumor growth, metastasis, and immune escape." (PMID 32150875, 2020). "Moreover, through functional in vitro studies, we showed that differences in galectin-1 level affected tumor cell proliferation, migration, and invasion." (PMID 31892852, 2020). "Galectin-1 levels have been assessed in multiple tumor types." (PMID 32486344, 2020). "Shikonin could downregulate MMP2 which can cleave or degrade ECM and promot tumor invasion and metastasis, but when decreases galectin-1 though shikonin fail to do it." (PMID 31892852, 2020). "LGALS1 plays a role in cell-cell and cell-matrix interactions, and in tumor progression." (PMID 32085797, 2020). "Galectin-1 stimulates angiogenesis and supports tumour cell proliferation in MM." (PMID 30813402, 2019). "This is important in light of the roles of galectin-1 in tumor progression and immune regulation." (PMID 31382488, 2019). "Galectin-1, a lectin with a broad range of biological activities, is differentially expressed by many cancer cells and is frequently found in the stroma surrounding tumour cells." (PMID 30813402, 2019). "Some tumor cells expressed galectin-1 in the cytoplasm at a low staining intensity and percentage." (PMID 30140386, 2018). "Increased galectin-1 expression in tumor cells eventually enhances H-Ras membrane localization and evokes the RAF proto-oncogene serine/threonine-protein kinase (Raf-1)/mitogen-activated protein kinase (MEK)/ extracellular signal–regulated kinases (Erk) pathway to strengthen the cell transformation." (PMID 29671787, 2018). "Therefore, we further investigated the localization of galectin-1 in the tumor at the protein level." (PMID 30140386, 2018).
tumor (continued). "The expression of TF might facilitate the tumor immune response evasion, since the TF epitope is a potent ligand for galectin-1 and -3, which are known to modulate the immune response." (PMID 30189652, 2018). "In continuation of our previous investigation on the role of galectin-1 in UBUC tumorigenesis, in this study, proteomics strategies were implemented in order to find more key signaling pathways which are initiated by the galectin-1 protein in tumor cells further to our existing findings." (PMID 29671787, 2018). "Furthermore, combining loss of galectin-1 with genetically engineered mouse models of PDAC (Ela-myc and Ela-KrasG12Vp53−/−) resulted in diminished stromal activation and tumor cell proliferation, and increased infiltration of cytotoxic T-cells." (PMID 30200666, 2018). "For instance, galectin-1 binds to H-RAS which drives tumor transformation." (PMID 30140386, 2018). "Furthermore, we see a statistically significant upregulation in members of the galectin family – galectin 3 and galectin 1 – a group of proteins that bind β-galactoside and whose expression correlates with tumour development and invasiveness." (PMID 29666124, 2018). "Galectin-1 may promote survival of hematological malignancies through direct action on tumor cells but also through effects on the tumor microenvironment." (PMID 29580262, 2018). "The staining of galectin-1 was scored in tumor cells and in the stromal compartment." (PMID 30140386, 2018). "Secondly, galectin-1 immunohistochemistry was performed on perpendicular tumor punches where the orientation of the tumor was unknown." (PMID 30140386, 2018). "It was proven to be upregulated by endogenous galectin-1, promoting tumor metastasis." (PMID 29254283, 2017). "PSC-derived Galectin-1 is involved in the cross-talk between the desmoplastic stroma and cancer cells in the tumor microenvironment, and may promote the malignant behavior of PDAC, resulting in poor prognosis." (PMID 29156810, 2017). "The high expression of Galectin-1 in PDAC, along with its positive relation with the expression of EMT markers and MMP9 expression, prompted us to investigate whether PSC-derived Galectin-1 functions as a tumor promoter." (PMID 29156810, 2017). "Whole-genome transcriptome profiling, in vitro and animal experiments revealed that interleukin 6, interleukin 8, chemokine (C-X-C motif) ligand 1, galectin-1, and selected proteins of the extracellular matrix (e.g., fibronectin) do have similar regulation during wound healing and tumor growth." (PMID 29072623, 2017). "Recent studies have demonstrated that chemokine production, PSC proliferation, collagen and fibronectin synthesis could be induced by galectin-1, and they were responsible for the tumor desmoplastic reaction around cancer cells." (PMID 29254283, 2017). "Our recent results have validated (galectin-1) gal-1 as a viable cancer target with broad potential, as differential stromal elevation of gal-1 over the tumor parenchyma has been reported in several cancers, including those of head and neck, ovary, breast, brain, colon, skin, and prostate." (PMID 29232825, 2017). "Different studies highlighted that galectin-1 could have different effects on cancer cell proliferation, depending on the localization of this lectin (intracellular or extracellular) and on the tumor type." (PMID 29258207, 2017). "Finally, in glioblastoma, galectin-1 induces a natural killer (NK) cell inhibition, mediated by the increased activity of tumor related immunosuppressive MDSCs." (PMID 29258207, 2017). "However, galectin-1 and integrin α5β1 protein expressed in tumor cells only in 82.86% (58/70) and 85.71% samples (60/70), respectively." (PMID 28842515, 2017). "Increasing evidence indicates that Galectin-1 expression is dysregulated in cancer, and may contribute to tumor invasion and metastasis, angiogenesis, and protecting tumors from host immune responses." (PMID 29156810, 2017).
tumor (continued). "As various promoters influence galectin-1 expression during tumor formation, galectin-1 might be a promising drug target and biomarker for PDAC." (PMID 29254283, 2017). "However, in the stromal cells of the tumor buds, LGALS1 was downregulated and candidate genes SERPINB5 and TM4SF4 were upregulated, as compared with the control." (PMID 28687755, 2017). "This review discusses the role of galectin-1 in the tumor microenvironment." (PMID 27649167, 2016). "Many studies have reported the immunosuppressive properties of galectin-1, which might correlate with the development of tumours." (PMID 27494859, 2016). "In addition, the dimers demonstrated regulatory effects in galectin-1 mediated tumor-cell apoptosis, homotypic cellular aggregation, and angiogenesis." (PMID 27649167, 2016). "Moreover, galectin-1 expression is lower in neoplastic hepatocytes of HCC tumours than in surrounding stromal tissue." (PMID 27494859, 2016). "This suggests a significant difference in the level of galectin-1 expression between benign and tumor tissue that could be manipulated as a target for tumor specific drug delivery." (PMID 27223428, 2016). "In this study, our results indicated that HSCs could promote tumour immune privilege and tumour progression through galectin-1 expression, while this function can be suppressed by miR-22." (PMID 27494859, 2016). "Although galectin-1 was detected in tumour hepatocytes, higher galectin-1 expression in stromal cells than in hepatocytes suggested that stromal cells might regulate galectin-1 expression in HCC." (PMID 27494859, 2016). "However, in addition to TNM stage, tumour differentiation also correlated with HSC-derived galectin-1 and CD3 expression." (PMID 27494859, 2016). "Tumor vascularization has been correlated with elevated levels of galectin-1 in the endothelium." (PMID 27649167, 2016). "Galectin-1, which is commonly over expressed in malignant cancer, mediates a variety of cellular processes in cancer progression by interacting with glycoconjugates in the tumor microenvironment." (PMID 27649167, 2016). "Moreover, endogenous galectin-1 plays a key role in tumour immune privilege due to its capacity to induce apoptosis in activated T cells, which is relatively similar to the immunomodulatory properties of HSCs." (PMID 27494859, 2016). "Galectin-1 modulates cell proliferation, adhesion, and migration, all of which are essential for tumorigenesis, and also regulates the interaction between tumour cells and components of the tumour microenvironment." (PMID 27494859, 2016). "Together, these results demonstrate the importance of galectin-1 in tumor immunosuppression." (PMID 27649167, 2016). "To conclude, tumor galectin-1 expression might be used as a marker for a more aggressive anti-cancer treatment." (PMID 26066796, 2015). "Thus, a novel role for the transcription factor LYAR in CRC has been revealed: LYAR promotes tumor migration and invasion by upregulating galectin-1 gene expression." (PMID 26413750, 2015). "In parallel to this preclinical work, we questioned whether increased galectin-1 expression levels were exclusively found at the tumor site or whether galectin-1 could also be detected in the serum of HGG patients." (PMID 26137448, 2015). "Furthermore, western blot analysis confirmed that the expression levels of galectin-1 in the tumor tissues from 15 patients were significantly higher than in matched adjacent non-tumor tissues." (PMID 26413750, 2015). "Galectin-1 was mainly expressed by fibroblasts in the tumor stroma." (PMID 26066796, 2015). "Galectin-1 tumor intensity independently correlated with poor survival, with a hazard ratio of 8.0." (PMID 26066796, 2015). "Although it is not yet fully elucidated, the role of galectin-1 in cancer-associated stroma is certainly an interesting issue due to the highlighted significance of tumor-stromal interactions." (PMID 26589590, 2015).
tumor (continued). "This is supported by the highest producers of galectin-1 in the tumor microenvironment in γδ T cells carrying the Vγ4 and, to a lesser extent, the Vγ2 (not shown) chains in mice, thus corresponding to subsets primarily located in the periphery rather than in the intestine." (PMID 25897427, 2015). "We therefore wished to compare the galectin-1 positivity with CA125 values in our tumor panel." (PMID 26589590, 2015). "Furthermore, tumor growth was significantly inhibited in CSCs xenografts with knockdown of galectin-1 as compared to CSCs treated with scramble siRNAs." (PMID 25605013, 2015). "Alternatively, galectin-1 serum levels may reflect an immune reaction to the tumor load from inflammatory cells that are known to express galectin-1." (PMID 26589590, 2015). "The aim of our study was to identify whether galectin-1, galectin-3, and/or 90K/Mac-2BP correlates with tumor staging in patients with CRC and to investigate their possible clinical role in the prediction of patients with CRC." (PMID 26448934, 2015). "Tumor galectin-1 expression was an independent predictor of poor disease-specific survival." (PMID 26066796, 2015). "To conclude, while tumor cell expression of galectin-9 seemed to represent a beneficial response, galectin-1 expression might be used as a marker for a more aggressive anti-cancer treatment." (PMID 26066796, 2015). "In the tumor microenvironment, galectin-1 induces angiogenesis and may facilitate metastasis by binding tumor cells to endothelial cells." (PMID 26066796, 2015). "In addition, we performed both qRT-PCR and western blot to demonstrate high expression of galectin-1 in EOC tumor specimens." (PMID 26589590, 2015). "Therefore, at least in part the galectin-1 expression in cancer-associated stromal tissue is due to the synthesis in stromal fibroblasts, and this stromal galectin-1 expression can be modulated by conditions of tumor microenvironment." (PMID 26589590, 2015). "Galectin-1 is widely distributed in many normal and pathological tissues and appears to be functionally polyvalent, such as regulating cell proliferation, differentiation and apoptosis, mediating tumor transformation, growth and so on." (PMID 24595374, 2014). "Galectin-1 suppresses T cell-mediated cytotoxic immune responses and promotes tumor angiogenesis." (PMID 25000307, 2014). "Besides its direct effects on tumor progression, galectin-1 also plays a role in tumor immune regulation by creating a bias toward a Th2 profile and activation of tolerogenic DC and IL-10 producing regulatory (Tr1) cells." (PMID 24658839, 2014). "All of these indicated PSCs derived Galectin-1 promote the tumor establishment and growth." (PMID 24595374, 2014). "PSCs derived Galectin-1 seem to be the key elements in the cross-talk between the parenchymal cells and the desmoplastic stroma,which may enhance metastatic potential of tumor cells and result in poor prognosis." (PMID 24595374, 2014). "Overexpression of galectin-1, a prototype member of this family, has been documented in many different tumor types, and in various aspects of tumor biology including migration and invasiveness, chemoresistance, angiogenesis, immune escape and malignant progression." (PMID 23530091, 2013). "In tumours, LGALS1 is regarded as a predictor of metastasis and a treatment target." (PMID 22279561, 2012). "Further, we hypothesized that expression of invasion mediators, and Galectin-1 specifically, would be elevated at the tumor-brain interface." (PMID 22583806, 2012). "Histological analysis did detect nuclear Galectin-1 in the tumour cells, a phenotype similar to the persistence of nuclear nucleolin expression in the presence of its inhibitors of transcription and translation, but cell surface matrix expression of Galectin-1 was below detection." (PMID 21779348, 2011). "We will discuss below the role in the tumor microenvironment of the sole galectin-1, -3, and -9." (PMID 24212939, 2011).
tumor (continued). "The only correlation found was with tumour size; sera from patients with larger primary tumours (>25 mm) gave significantly higher average yields of galectin-1 bound glycoproteins (2.8 mg/ml serum, p = 0.0028) than smaller primary tumours (<25 mm, 1.8 mg per ml serum)." (PMID 22028908, 2011). "These genes are involved in the regulation of immune/inflammatory response (Lgals1, Ptgds, Tff2, Ubd), tumor angiogenesis (Lgals1, Esm1, Ndrg1), epidermal growth factor signaling (Erbb4, Nrg1), response to tissue injury (Tff2, Vnn1), and gene transcription (Id3, Ifrd1)." (PMID 19340302, 2009). "Galectin-1 has been shown to affect cell migration of tumours and influence their invasiveness." (PMID 15785741, 2005). "We hypothesised that tumour cells may impair T-cell effector functions through secretion of galectin-1 and that this mechanism may contribute in tilting the balance towards an immunosuppressive environment at the tumour site." (PMID 15785741, 2005). "While the endogenous protein may function as a growth-promoting factor, exogenously added galectin-1 specifically suppresses tumour cell proliferation." (PMID 15785741, 2005). "In addition, recent evidence indicates that galectin-1 contributes to tumour evasion of immune responses." (PMID 15785741, 2005). "It has been recently demonstrated that intracellular galectin-1 may play a key role in the initiation of transformed phenotype of tumours." (PMID 15785741, 2005). "Being aware of this, we present a comprehensive overview of galectin-1 (Gal-1), the most extensively studied member of the galectin family, with a specific focus on its immunological functions, its involvement in tumor biology, and its potential as a therapeutic target in tumor immunotherapy." (PMID 40178639, 2025). "While Galectin-1 (Gal-1) has been extensively reported to regulate not only tumor-intrinsic properties but also the broader tumor microenvironment, including immunity, the experimental design of this study is primarily focused on evaluating the endogenous tumor-related effects of Gal-1." (PMID 39941722, 2025). "These include NT5E (CD73) and ENTPD1 (CD39) which are involved in immunosuppressive adenosine signaling, LGALS1 (galectin-1) and TGFB1, which encode for anti-inflammatory cytokines, and CD274 (PD-L1), which binds to PD-1 to initiate an inhibitory signaling pathway in anti-tumor immune cells." (PMID 40277917, 2025). "Among these, LGALS1 expression levels showed a significant positive correlation with tumor cell sensitivity to four agents – zoledronate, staurosporine, JNJ-38877605, and pazopanib – indicating that higher LGALS1 might render tumors more susceptible to these drugs." (PMID 41164132, 2025). "Notably, iCAFs may induce CD8 + T cells apoptosis and impair their anti-tumor functions by interacting with CD8 + T cells PTPRC receptors via Galectin-1 (LGALS1)." (PMID 37833788, 2023). "Thus, galectin-1 may favor the immunosuppressive tumor microenvironment by exerting an important role in modulating central monocytes and macrophages." (PMID 37047471, 2023). "Galectin-1 and other galectins ultimately stabilize the microenvironment for tumor cell growth by participating in specific metabolic processes of tumor cells: meeting the metabolic demands of tumor cells, inhibiting the function of immune cells, and creating an immunosuppressive microenvironment." (PMID 36428567, 2022). "Furthermore, tumors may exploit the ability of EC to express PD-L1 for immune evasion since tumor galectin-1 production increases EC PD-L1 expression, thus reducing tumor T cell infiltration." (PMID 35216427, 2022).